CD4 (CD4 molecule)
Diseases named in the same sentence as CD4 in open-access papers (continued):
Sharing a sentence is not in itself a finding about the gene and the disease.
tumor (continued). "The injection of VV-GM alone did not significantly affect Treg cells (CD4+FoxP3+) in tumor infiltrates, but the injection of VV-iPDL1/GM reduced Treg cells to a level lower than that in PBS-treated tumors, resulting in a robustly enhanced CD8+ T cells/Treg ratio." (PMID 32170083, 2020). "Six days after LLC tumor implantation, mice were given RAD001 daily at 0.01 mg/kg or 0.05 mg/kg or vehicle control for 8 days, followed by adoptive transfer of preactivated Thy1.1+ (OT-I) CD8+ and OT-II CD4+ T cells expressing the IFN-γ–yellow fluorescent protein (YFP) reporter." (PMID 32759497, 2020). "Moreover, these genes may play important roles in promoting tumor angiogenesis (CXCL13, ZAP-70, and CCL19), tissue remodeling (ITGAM and ITGB2), and immunosuppression (CD4 and IL-10) in cancer cell lines or samples." (PMID 32509861, 2020). "In addition, our in vivo studies also revealed that exposure to moderate SMFs promoted granule and cytokine secretion from tumor-infiltrating CD8+ T cells from PyMT mice but did not affect cytokine secretion from CD4+ T cells." (PMID 32884074, 2020). "In cancer, CD4 T cells have received less attention than CD8 T cells because tumor cells have reduced, and often lacking, expression of MHC-II molecules and because the Class II-associated invariant chain peptide (CLIP) prevents presentation of endogenous peptides." (PMID 32630460, 2020). "Lentiviral vectors have been broadly used to generate NK cells expressing CARs with 1st, 2nd and 3rd generation designs which target different tumor antigens including CD19, CD20, TF in TNBC, CD33, CD7, CD22, ErbB2, EpCAM, Glypian-3 (GPC3), CS1, EGFR, B cell maturation antigen (BCMA) and CD4." (PMID 32707982, 2020). "miR‐17 and especially miR‐19b appeared to strongly correlate with the proportion of CD3+ cells in the tumor infiltrate, while miR‐195 consistently showed positive associations with both proportion and density of CD3+, CD4+, CD5+, CD8+ and FOXP3+ cells, but not CD20+ cells." (PMID 33024560, 2020). "Moreover, the number of CD4+ and CD8+ T cells in the tumor tissue of YYWY group both increased, which may be caused by the increased number of tumor infiltrating DCs and T cells proliferation after YYWY treatment." (PMID 32595493, 2020). "Analysis of the lymphoid immune cell subtypes in MyC-CaP demonstrated an increased tumour infiltrate of CD45+CD4+CD25+FoxP3+ Treg cells, and a non-significant reduction in the proportion of CD45+CD3+CD8+ T-cells, in 3 × 5 Gy RT-treated tumours versus untreated controls." (PMID 32641865, 2020). "The Log-rank test and Kaplan-Meier survival analysis showed that high levels of VGLL3 and macrophages were significantly associated with poor survival (P < 0.05), whereas tumor purity, B cells, CD8+ T cells, CD4+ T cells, neutrophils, and dendritic cells were not (P > 0.05, data not shown)." (PMID 31992826, 2020). "Depletion of CD8 T-cells, but not CD4 or NK cells, abrogated the anti-tumor effect." (PMID 32974162, 2020). "The immunosuppressive effect of these M-MDSCs on CD4+ T cells was found primarily to be due to the increased IL-10 production, which in turn, inhibited anti-tumour immune responses, through inhibiting the production of IFN-γ and IL-12, and therefore enhancing tumour growth." (PMID 32931721, 2020). "Notably, not only was the frequency of both CD4+ and CD8+ T cells expressing A2aR in the tumor microenvironments elevated relative to the peripheral blood, but the amount of A2aR expression, as detected by the mean fluorescence intensity (MFI), was also significantly elevated." (PMID 32721947, 2020). "Tumours, which lose MHC expression or acquire upstream defects in antigen presentation, will be relatively resistant to immune‐mediated elimination by tumour‐specific T‐cells, resulting in impaired activation of CD4+ (MHC‐II recognition) and CD8+ T‐cells (MHC‐I recognition)." (PMID 35845006, 2020). "In addition, CD4+ and CD8+ T cell tumour infiltration was enhanced." (PMID 32575876, 2020).
tumor (continued). "The presence of IL2 within the tumor through intratumoral IC may have a crucial role in driving this proposed T-dependent antibody response, as IL2 has been shown to be critical for CD40-mediated activation of naïve B cells by CD4 T cells." (PMID 32849544, 2020). "We describe that moDCs stimulated by tumor supernatant of the highly cytotoxic NB-PDT condition are able to provide the adequate stimulatory signals for the proliferation of CD4+ T cells and differentiation towards Th1 CD4+ effector T cells, as indicated by the substantial release of IFNγ." (PMID 32326519, 2020). "Taken together, these results suggest that the CD4+ T and NK cells have been activated and effector memory CD8+ T cells have at some point expanded in response to expression of the immunosuppressive ligand in the tumor in a subset of the metastatic IBC patients." (PMID 33267869, 2020). "Interestingly, CD4+FOXP3+ T cells had a close interaction with CD8+ T cells rather than tumor cells." (PMID 32377339, 2020). "The early observation that CTLA‐4 blockade could enhance tumor Ag‐specific CD4+ T cell priming but could not overcome the eventual tolerization of these cells highlighted the contribution of alternative pathways to the regulation of T lymphocyte function." (PMID 32508018, 2020). "Chemotherapy can augment tumor immunity by decreasing the number of Immunosuppressive cells like myeloid-derived suppressor cells (MDSC) or T-regulator cells in the microenvironment which can lead to an accumulation of helper T-cells on site and by promoting anti-tumor CD4+ T-cell phenotype." (PMID 32405337, 2020). "DCs function is a bridge between the innate and adaptive immune systems and acts as attractive targets for tumor immunotherapy because of their unique ability of activating primary immune responses through the presentation of antigens to naïve CD4+ and CD8+ T cells." (PMID 32595493, 2020). "Hence, CD4+CD127lowFOXP3+ cells, which are usually classified as regulatory T cells (TREG), might contribute to tumor development by suppressing pro-inflammatory cytokines." (PMID 32100077, 2020). "Our results demonstrated that IRE not only increased the tumor‐infiltrated CD8+ T cells, which acted as a key contributor to the superior antitumor efficacy in suit, but also enhanced the immune memory by elevating the proportion of memory CD4+ and CD8+ T cells." (PMID 32508058, 2020). "More detailed immunophenotyping of tumor leukocyte populations revealed no consistent changes in the proportion of CD19+ B cells, F4/80+ macrophages, CD11b+Ly6G+ myeloid cells, NK cells, or CD4+CD25+FoxP3+ regulatory T cells associated with loss of Raptor from tumor ECs." (PMID 32759497, 2020). "On the other hand, systemic therapy with mCelyvir resulted in non-significant increased mean values of CD8 and CD4 T lymphocytes per tumor volume, expressing markers of recent and sustained T cell activation (OX40 among CD8, PD1 and LAG3 among both CD4 and CD8, and TIM3 among CD4)." (PMID 32064039, 2020). "The immune alteration mainly includes, but is not limited to, increased tumor infiltration of CD3+ and CD8+ T cells, reduction of immunosuppressive FoxP3+ regulatory T cells, and an increased ratio of CD8+ T cells/regulatory T cells (CD4+FoxP3+) (a hall mark of clinical efficacy)." (PMID 32050597, 2020). "Activated CD4+ T cells contribute to antitumor immunity not only by concurring in CTL activation, but also through the production of IFN-γ that activates NK cells and macrophages, inhibits angiogenesis, regulates the generation of tumor stroma, and promotes direct cytolytic effects." (PMID 32486257, 2020). "Murine models depict tumor antigen-specific T-cell responses when radiation-induced tumor cell death released HMGB1, which not only augmented the engulfment of antigenic materials by DCs via TRL4 but also mediated cross-presentation of tumor antigens into CD4 and CD8 T-cells." (PMID 32340275, 2020).
tumor (continued). "While effector CD4 T cell depletion does not negatively impact all immunotherapies, there is a growing appreciation of the contributions of CD4 T cells in mediating anti-tumor responses." (PMID 33597954, 2020). "Having previously shown that SCARF1 mediates the specific recruitment of CD4+ T cells to LSEC in vitro, under conditions of physiological flow, we aimed to determine whether it could play a role in the recruitment of TILs to the HCC tumor microenvironment." (PMID 34354939, 2020). "The cells infiltrated in tumor-bearing p2rx7−/− contained an immunosuppressive microenvironment, compared to those growing in the wtAT background, with fewer effector T cells (Teff) (CD8+ and CD4+), increased Treg cells (CD4+, CD25+, Foxp3+) and a decline in cytotoxic effector CD8+ T cells (Tcyt)." (PMID 32635260, 2020). "In the process of tumour immune escape, Tregs can secrete TGF-β, IL-10, and IL-35 (Ebi3-IL-12α heterodimer), which downregulate antitumour immunity, suppress antigen presentation by DCs, CD4+ T helper (Th) cell function and generate tumour-specific CD8+ cytotoxic T lymphocytes (CTLs)." (PMID 32680511, 2020). "Besides, helper CD4+ T cells were described to mediate entry of cytotoxic CD8+ T cells into tissues, thus potentially contributing to cytotoxic CD8+ T cell recruitment to tumor sites." (PMID 32674488, 2020). "Therefore, a low CD4:CD8 ratio may reduce the number of Treg cells, which decreases the inhibitory effect on the tumor." (PMID 32160735, 2020). "Consequently, Ag delivery to CD1c+ DCs may further enhance tumor‐specific CD4+ T‐cell responses, even though anti‐CLEC9A and anti‐DEC‐205 Abs promote CD4+ T‐cell responses similarly after uptake by CD141+ DCs." (PMID 32547743, 2020). "Furthermore, the changes in CD4+ and CD8+ T cell cytokines produced in the tumor microenvironment after G-CSFR−/− cell injection led us to test the ability of IFNγ or IL-17A alone to inhibit tumor growth." (PMID 33042110, 2020). "Additionally, in a humanized-mice model of lung cancer, vaccination with iPSCs + CpG was shown to increase the percentage of splenic APCs and cytotoxic T cells, circulating effector/memory CD4+ and CD8+ T cells and tumor-infiltrating CD8+ T cells, while decreasing Tregs." (PMID 33266109, 2020). "To test this hypothesis, we analyzed the relationship between rhythm genes and immune pathways, and the correlation between rhythm genes and four tumor‐infiltrating lymphocytes (TIL), including M1 macrophages, M2 macrophages, CD4+ T cells and CD8+ T cells, respectively." (PMID 31927791, 2020). "CD4+ T cell help is less likely to be delivered in cancer than in infection for the following reasons: Tumor cells generally do not express PAMPs and may only exude DAMPs under specific circumstances." (PMID 33123174, 2020). "One tumor-promoting mechanism could be immune response inhibition by tumor antigen presentation via MHC class II receptors present on the macrophage-tumor cell hybrids, directly affecting the CD4+ T cell responses, which could be targeted therapeutically." (PMID 32182935, 2020). "A more significant secretion of IFN-γ and TNF-α was found in the DCs cocultured with the supernatants from tumor cells infected with NDV-MIP3α compared with the supernatants of cells infected with NDV-WT, indicating a great benefit to the activation and differentiation of CD8+ and CD4+ T cells." (PMID 32759233, 2020). "However, as these markers are not exclusive to Treg, detection of FOXP3 in tumor tissue is inferred to represent CD4+CD25+FOXP3+ Treg." (PMID 33013886, 2020). "A higher CD4+ could be expected to be an earlier event in the sequence of immune process, whereas a preponderance of CD68+ could be a late event reflecting the culmination of the immune process and scavenging the dead tumor cells by CD68+ macrophages." (PMID 32596144, 2020).
tumor (continued). "However, the numbers of Iba-1-positive macrophages (pan-macrophages), CD204-positive macrophages (M2-like macrophages), CD3-positive lymphocytes, CD4-positive lymphocytes, and CD8-positive lymphocytes in subcutaneous tumor tissue remained unchanged following epimedokoreanin B administration." (PMID 32256354, 2020). "In addition, our evidence that spatial heterogeneity can provide unique information about the drug response role of CD4+ and CD8+ T cells could be expanded to understand their localization within the tumor." (PMID 32554190, 2020). "Moreover, transfer of CD4+ T cells inhibited tumor progression in BR5-FOXL2, but not in 4T1-FOXL2, compared with control CD3+ T cells (4T1, nonsignificant; BR5 CD4+, P < 0.03)." (PMID 32814714, 2020). "However, the current ACT is mainly focused on CD8+ cytotoxic T lymphocytes, while the anti-tumor efficacy of CD4+ T cells has not been fully explored." (PMID 32508847, 2020). "However, CD4+ T cell densities at baseline in the tumor or at the invasive margin were not shown to be predictive of response to pembrolizumab." (PMID 33013886, 2020). "Dendritic cell-derived MHC class II molecules and tumor-derived antigenic peptides travel by separate routes and converge to form MHC class II-peptide complexes in DC/tumor FCs, where MHC class II-antigenic peptide complexes are expressed on the DC/tumor FC surface and presented to CD4+ T cells." (PMID 32150821, 2020). "Therefore, CD4, CD8, Foxp3, GrB, IL10, and CD68 immune cell markers were studied in order to explore if differences around EBV-infected CG cells and EBV+ tumor cells derived from GC cells could be involved in the malignant transformation." (PMID 31963774, 2020). "This has implications for extrapolation of our immune-cold status as defined by the combined low-density cell counts for CD3, CD4 and CD8 IHC into scoring of endoscopic diagnostic biopsy samples that are taken from the luminal aspect and not the advancing tumour edge." (PMID 32684627, 2020). "Since both CD4+ and CD8+ T cells from G-CSFR−/− mice showed a similar effect when adoptively transferred into tumors, we also hypothesized that cytokines produced by CD4+ and CD8+ T cells could be playing a critical role in promoting tumor growth." (PMID 33042110, 2020). "Indeed, CD4+ T cell depletion decreased tumor burden in KPC-OG mice, and further analysis demonstrated that IL17-secreting TH17 cell was increased in its pancreas and had a key role in mediating tissue fibrosis and promoting tumor progression." (PMID 32616713, 2020). "Reversal of protumour activity of T lymphocytes could be achieved by the development of a methodology to suppport the transformation of CD4+ T cells toward Th1 cells, hence reinforcing the activation and infiltration of CD8+ T cells into the tumour microenvironment of HCC." (PMID 32466214, 2020). "This is a representative IF figure for the markers cytokeratin, PD-L1, CD4, CD8, perforin and granzyme B. Image analysis of IF staining of tumor sections revealed enhanced CD4 T cells, CD8 T cells, perforin and granzyme B but reduced tumor-specific cytokeratin following therapy." (PMID 33167311, 2020). "Besides, DT induced deletion of Tfr cells did not influence tumor infiltrating Treg cells as well as effector CD4 T and CD8 T cells, evidenced by comparable number of Treg cells, Foxp3–CD44+CD4+ T and CD44+CD8+ T cells." (PMID 32477338, 2020). "Therefore, we investigated whether promoting MDSC differentiation and inhibiting its immunosuppressive functions by HSD would affect the proliferation and functions of CD4+ T and CD8+ T cells in tumour animal models." (PMID 32265505, 2020). "Interestingly, treatment with R-115 increases the number of CD4+ and CD8+ T cells infiltrating into the tumor microenvironment, while the vast majority of CD4+ and CD8+ T cells in the R-LM113 treatment group accumulated at the edge of the tumors, indicating the effects of IL-12." (PMID 32050597, 2020).
tumor (continued). "However, a significant increase in tumor-infiltrating lymphocytes (TILs) was observed in tumors treated with OAd-MSCs, as well as a significant reduction of the CD4+/CD8+ ratio, due to the reduced and increased levels of CD4+ and CD8+ T cells, respectively." (PMID 32708639, 2020). "In addition to expression in most CD4+CD25+ ATLL, CCR4 is expressed in approximately 30–65% of PTCL tumor cells, including high expression (~ 65%) in ALK-negative ALCL, variable expression (30–40%) in PTCL/NOS, AITL, and transformed MF, while rarely expressed in ENKTL or ALK-positive ALCL." (PMID 32448357, 2020). "In the case of CD4+ T cells, our study based on flow cytometry data showed significantly higher numbers of naive CD4+ T cells but not Th1 cells and Th17 cells in the tumor microenvironment of HPV-positive HNSCC samples compared to those in the tumor microenvironment of HPV-negative samples." (PMID 33042814, 2020). "Consequently, in CD4+ T cells with SHP2 knockout, STAT1 is hyper-activated, triggering increased Th1 differentiation and IFN-γ production, which further enhances the activity of CD8+ CTLs for anti-tumor immunity." (PMID 33419310, 2020). "These are complemented by the higher CD4/CD8 ratio in metastases, which could portend the presence of regulatory T cells further known to inhibit anti-tumor responses, though our inability to evaluate additional markers prevents us from confirming this hypothesis." (PMID 33148332, 2020). "Interestingly, other TILs, the CD4+ T cells, stay in the peritumoral zones rather than tumor regions." (PMID 32781527, 2020). "Our results provide evidence that patients with increased CD4+FOXP3+ T cells and CD8+ T cells will not only have a favorable prognosis but may also be candidates for ICB as a result of high IFN‐γ and PDL1 expression in the tumor." (PMID 32377339, 2020). "Indeed, treatment induced a specific decrease in the number of activated Tregs (CD4+/Foxp3+/CTLA4+) in the tumor microenvironment, without modulating Ki67 and HLA-DR activation markers." (PMID 32681091, 2020). "Similarly, anti-CD4 antibody alone did not significantly influence tumor growth in RaptorECKO mice, although CD4+ T cells were neutralized." (PMID 32759497, 2020). "Interestingly, the combined treatment of pemetrexed and anti-PD-L1 antibody synergistically amplified the numbers of both CD4+ and CD8+ TILs even more in the tumor surroundings, indicating that the immunosuppressive tumor microenvironment has been altered through this combinational treatment." (PMID 33243934, 2020). "A recent study has indicated that the percentages of CD4+CD25+FOXP3+Treg cells and CD4+IL-17+Th17 cells were significantly higher in HCC patients than in the healthy individuals; Moreover, the increased percentages of Treg and Th17 cells were closely related to the tumor stage and tumor size of HCC." (PMID 32847505, 2020). "In addition, the expression of CXCL9, CXCL10, and CXCL11 was significantly correlated with the presence of tumor-infiltrating cytotoxic CD8+ T cells and CD4+ TH1 effector cells, which represent an independent positive predictor of prolonged disease-free survival of CRC patients." (PMID 33419310, 2020). "As expected from their increased tumor numbers and tumor sizes, His-SjE16.7- and GST-SjE16.7-treated mice had a significant increase in the frequency of inflammatory myeloid cells (CD11b+) in their spleens but significantly lower frequency of CD4+ and CD8+ T cells." (PMID 32973746, 2020). "Interestingly, the upregulation of PD1 seen in CD4+FoxP3−PD1+ TILs was due to their presence in the tumor and not because of overall systemic changes." (PMID 32690667, 2020). "Th1 cells (CD3+ CD4+ T-bet+ Foxp3-) are also increased in the PBMC of HCC patients (2.41 ± 1.60), and even more increased in their peritumoral tissue (4.35 ± 1.49) and at the tumor site (12.97 ± 7.39); showing that the tumor microenvironment is an ongoing inflammatory response." (PMID 32182707, 2020).